RARB (retinoic acid receptor beta)
Diseases named in the same sentence as RARB in open-access papers (continued):
Sharing a sentence is not in itself a finding about the gene and the disease.
lung carcinoma (continued). "Methylation has been shown to be a mechanism that inactivates genes, and studies have demonstrated that demethylating agents such as DAC can help with re-expression of RARβ in silenced cell lines and tumor samples in lung cancer." (PMID 35631448, 2022). "A study reported an in vitro increased expression of RARα and RARγ and reduced RARβ in lung carcinoma cell lines." (PMID 35631448, 2022). "Treatment of bronchial biopsy specimens and lung cancer cell lines with 13-cis-RA (13cRA) showed an increase in RARβ expression." (PMID 35631448, 2022). "A report showed that RARβ is increased in expression in lung cancer cell lines, and CD437, which binds selectively to nuclear RARγ, can hamper cell growth and cause apoptosis in ATRA-resistant NSCLC cells." (PMID 35631448, 2022). "RARβ gene has been reported to be silenced in most non-small cell lung cancer (NSCLC) and is associated with an increased risk of lung cancer." (PMID 33995625, 2021). "This study aimed to understand the role of RARβ in regulating cell growth and differentiation of lung cancer stem cells." (PMID 33995625, 2021). "For example, in lung cancer cells A549 and H460 treated with curcumin, the RARβ expression was increased at mRNA and protein level and decreased tumorigenicity." (PMID 33995625, 2021). "ATRA can induce the apoptosis of NSCLC CSCs through activation of RARβ and its ability to down-regulate the CSCs markers in lung cancer cells." (PMID 32293355, 2020). "The RARβ is also known as tumor suppressor and the major target gene of retinoid action, and an enhanced level of RARβ protein exhibited its growth inhibitory action of lung cancer cells." (PMID 32293355, 2020). "It was reported that CGI methylation around the translational start site in the retinoic acid receptor beta (RAR-ß) gene dramatically corresponded to its expression in murine lung cancers compared to methylation at the promoter region located in same CGI." (PMID 26695186, 2015). "The pooled odds ratio (OR) of RARβ promoter methylation in lung cancer tissue versus autologous controls were calculated." (PMID 24796328, 2014). "For instance, in primary lung tumors as well as in lung cancer cell lines, the expression of retinoic acid receptor β (RARβ) is significantly decreased." (PMID 24212637, 2011). "On the other hand, overexpression of RARβ into lung cancer cells suppresses their tumorogenicity in nude mice." (PMID 24212637, 2011). "In murine models of cigarette smoke-induced lung cancer, hypermethylation of the TSGs, death-associated protein kinase 1 (DAPK1) and the retinoic acid receptor beta (RARB), is seen at the earliest histological stage of adenocarcinoma development." (PMID 21487403, 2011). "The findings suggest that smoking related biological pathways leading to the development of lung cancer involve not only hypermethylations of p16, DAPK and RARβ promoters but also genetic polymorphisms of CYP1A1 and GSTM1 genes." (PMID 20704749, 2010). "Our findings reported the percentage for p16, DAPK or RARβ methylated was the 48.67%, 58.67% and 60.00% in the tumor tissues of patients with lung cancer, respectively." (PMID 20704749, 2010). "The study examined the relationship between polymorphisms in CYP1A1 and GSTM1 and aberrant methylation of p16, DAPK and RARβ in lung cancer." (PMID 20704749, 2010). "This is our aim when validating extensively research tools, focused on Retinoic Acid Receptor beta, whose major role in lung cancer is documented." (PMID 19961602, 2009). "In the same study, it was also demonstrated that treatment of lung cancer cell lines with the demethylation agent 5-aza-2'-deoxycytidine (5-AZA-CdR) can restore RARβ expression." (PMID 18625040, 2008). "The other three genes analysed in this study RASSF1A, BLU and RARβ are known to be methylated in lung cancer and all have shown functional characteristics of tumour suppressor genes." (PMID 18594535, 2008).
lung carcinoma (continued). "RARβ expression is decreased in breast and lung cancer compared with normal tissues suggesting that regulation of RARβ expression has a role in malignant progression." (PMID 12942109, 2003). "It was found by using methylation‐specific PCR that the high percentage of promoter methylation in the RARβ and RASSF1A genes promotes lung cancer, such that carriers who have aberrant methylation in the promoter of two genes are at a higher risk of lung cancer than carriers of only one gene." (PMID 37901797, 2023). "Of note, RARβ expression is often lost or reduced in a large percentage of lung cancer." (PMID 36413416, 2023). "In BEAS-2B cells, this compound increased RARβ mRNA levels, although this impact was less significant in A549 cells, suggesting that this compound could be a promising chemopreventive drug for lung cancer." (PMID 35631448, 2022). "Lung cancer cell lines and bronchial biopsy specimens have an aberrant expression of RARβ." (PMID 35631448, 2022). "Previous research has shown that RARβ expression is reduced in lung cancer in vitro and in vivo, implying that RARβ could have tumor-suppressive effects in lung carcinogenesis." (PMID 35631448, 2022). "The aberrations of the RARβ network are frequent in human lung cancer cell lines." (PMID 35631448, 2022). "This promoter methylation was thought to be one of the mechanisms that can silence RARβ in lung cancer, and demethylation using different chemicals might be a useful approach in combating lung cancer." (PMID 35631448, 2022). "RARβ can mediate retinoid action in lung cancer cells by promoting apoptosis." (PMID 32293355, 2020). "However, a fundamental question that remains unanswered is how ATRA and RARβ trigger apoptosis in lung cancer cells." (PMID 32293355, 2020). "Combinatorial treatment of retinoids with EGFR-TKIs drugs in EGFR-TKIs resistance lung cancer cells promotes the activation of GATA6 and then inhibits the activation of EGFR/Wnt signaling pathways and favors the association of RXR, RARβ, and cellular retinoic acid binding protein-2 (CRABP2)." (PMID 32293355, 2020). "In addition, curcumin can increase RARβ expression at the mRNA and protein levels in lung cancer A549 and H460 cells, indicating that curcumin is able to inhibit RARβ promoter methylation." (PMID 28008143, 2017). "Other studies have demonstrated that the RARB promoter is hypermethylated in colorectal and lung carcinomas and that this methylation could account for the RARB downregulation." (PMID 26929741, 2016). "Thus, a meta-analysis about the relationship of RARβ promoter methylation between lung cancer tissue and autologous controls was done in order to better identify the correlation of methylation status between cancer tissue and autologous samples." (PMID 24796328, 2014). "In addition, a possible association was found between null GSTM1 and NSCLC with promoter hypermethylation of the DAPK or RARβ gene, implying effect of GSTM1 polymorphism on the aberrant methylations of TSG in lung cancer." (PMID 20704749, 2010). "However, considering that RARβ was highly expressed in the lung cancer cell line H292 and despite this, they are ATRA-resistant cells, the authors speculated that probably there were others factors differently expressed among the different cell lines." (PMID 32012980, 2020). "Epigenetic Indicators for Early Detection of Lung Cancer: Hypermethylation of genes like RARB, CDKN2A, and MGMT have emerged as promising biomarkers for lung cancer early detection, prognosis, and prediction of therapeutic response." (PMID 39982247, 2025). "Methylation of L1RE1, RARB, and RASSF1 serve as potential biomarkers for the differential diagnosis of lung cancer." (PMID 36741260, 2023). "In clinical practice, many of these DMRs have the potential to predict disease progression, including in patients with stage IV lung cancer (SHOX2, RARB/RASSF1A, RARB, RASSF1A/APC, DCLK1, BRMS1, SOX17, SFN, CHFR, and APC/RASSF1A/CDH13/CDKN2A)." (PMID 36765815, 2023).
lung carcinoma (continued). "The methylation of L1RE1, RARB, and RASSF1 acts as potential disease specific biomarkers for predicting the prognosis of lung cancer." (PMID 32218699, 2020). "Within the validation dataset (27 lung cancer cases and 38 benign controls) L1RE1, RARB, and RASSF1 were analyzed successfully." (PMID 29851970, 2018). "Abundant evidence manifests that a variety of well-known DNA methylations can be used as a promising biomarker for the early diagnosis of lung cancer, such as p16, RASSF1A, APC, MGMT, DAPK and RARβ." (PMID 28644424, 2017). "The most widely studied epigenetic event in relation to lung cancer included the promoter hypermethylation of p16, DAPK or RARβ gene." (PMID 20704749, 2010). "We studied the methylation status of five genes, p16INK4a, RASSF1A, APC, RARβ and CDH13, that are frequently methylated in lung cancers and that are considered to play an important role in the molecular pathogenesis of lung cancers." (PMID 15266335, 2004). "The present study examined the relationship between methylation of five genes (p16INK4a, RASSF1A, APC, RARβ and CDH13) and patient survival in 351 cases of surgically resected lung cancers." (PMID 15266335, 2004). "For instance, in lung cancer A549 and H460 cells, CUR significantly upregulates RARβ TSG expression at both the mRNA and protein levels; CUR acts through the inhibition of DNA methyltransferases and the subsequent reactivation of RASSF1A in cancer, leading to its therapeutic effects." (PMID 37731740, 2023). "The usefulness of methylation signatures in the ctDNA of lung cancer was demonstrated in the serum of 200 patients by identifying hypermethylated promoter regions of tumor suppressor genes (MGMT, CDKN2A, INK4A, RASSF1A, DAPK, and RARB." (PMID 36765815, 2023). "In lung cancer, the retinoic acid receptor beta (RAR-β) has been found to be absent in varying degrees in all malignant tumor types." (PMID 28587272, 2017). "In addition, only a relative small study has examined the relationship between polymorphisms in XRCC1, GSTM1, GSTP1, NQO1, and MPO and aberrant methylation of p16, RARβ and MGMT in lung cancer." (PMID 20704749, 2010). "Also, DNA methylation levels of tumor suppressor genes, including death-associated protein kinase 1 (DAPK1) and retinoic acid receptor beta (RARB), are higher in lung cancer tissues than noncancerous lung tissues." (PMID 35356464, 2022). "Previous reviews have identified that the DNA methylation patterns in lung cancer were altered, where genome-wide hypomethylation, and hypermethylation of the promoter regions of several tumor suppressor genes, such as DAPK, RASSF1A and RARβ, were commonly observed." (PMID 32899527, 2020). "L1RE1 in combination with either RARB or RASSF1 could function as biomarkers for separating lung cancer and non-cancerous tissue and could be useful for samples of limited size such as biopsies." (PMID 29851970, 2018). "Mice given 9cRA supplementation exhibited significantly decreased tumor multiplicity and a trend toward lower tumor incidence, implying that 9cRA may protect against lung cancer, with this effect mediated in part by 9cRA activation of RARβ but not COX2 transcription suppression." (PMID 35631448, 2022). "However, the authors underlined that both ATRA resistance and hypoacetylation were attributable to methylated CpG islands adjacent to RARE in the RARβ promoter, in some cell lines but not in others, suggesting that multiple mechanisms contribute to this transcriptional defect in lung cancer cells." (PMID 32012980, 2020).
lung carcinoma (continued). "Indeed, expression of RARβ2 in RARβ-negative lung cancer cells has been shown to restore retinoic acid-induced growth inhibition, and transgenic mice expressing antisense or other constructs that down-regulate RARβ2 developed lung cancer." (PMID 25806093, 2015). "As SR11302 is a known compound with strong anti-AP-1 activity with selective binding with RARα and RARΥ, but not with RARβ and RXRα, it provides important evidence that the AP-1 complex may play an important role in CTC survival and, ultimately, tumor metastasis in lung cancer." (PMID 29177791, 2017). "RARβ, CDKN2A, DAPK, RASSF1A and MGMT were examined, and the analysis showed that a patient having methylation of just one gene had an odds ratio of 5.08, meaning they were approximately five times likely to have lung cancer than patients without any methylated genes." (PMID 23870182, 2013).
prostate carcinoma (29 papers, 2004 to 2024). A carcinoma that arises from epithelial cells of the prostate gland. "Suppression of RARβ causes resistance to retinoic acid-associated growth arrest in breast and prostate cancer cells and in F9 teratocarcinoma cells." (PMID 18166136, 2007). "Similarly, RARB methylation was associated with a higher prostate cancer risk among American patients." (PMID 33883026, 2021). "This is in contrast with the fact that RARB has been found to be preferentially hypermethylated in early stage rectal tumours along with high-grade cervical intraepithelial lesions and high-risk prostate cancer." (PMID 28700744, 2017). "For example, in prostate cancer, the fifth major cause of cancer-related mortality globally, hypermethylation of certain tumour suppressor genes, such as GSTP1, RARB, APC and RASSF1, has been observed during the early stages of the disease." (PMID 39661598, 2024). "For example, hypermethylation of RARB promoter genes is a significant biomarker in diagnosing prostate cancer." (PMID 39661598, 2024). "Intuitive and biologically interpretable methylation state thresholds are inferred and DMCs are identified, including those related to genes such as GSTP1, RASSF1 and RARB, known for their role in prostate cancer development." (PMID 39661598, 2024). "The capability of the BMMs is demonstrated to appositely model the beta values, to objectively identify thresholds and to identify existing and novel DMCs, including those related to genes implicated in prostate cancer, such as GSTP1, RARB and RASSF1." (PMID 39661598, 2024). "On performing gene ontology analysis, CpG sites in cluster 2 were found to be related to known genes e.g., RARB, GSTP1, RASSF1, SFRP2, which are implicated in prostate cancer." (PMID 39661598, 2024). "Most primary prostate cancer cells and the prostate cancer cell lines DU-145 and PC-3 express RARα and RARγ; the LNCaP cell line additionally expresses RARβ." (PMID 36768694, 2023). "It has been reported that there was higher frequency of RARB hyper methylation in poor prognosis cases compared with good prognosis in a sample of Iranian prostate cancer patients." (PMID 33883026, 2021). "We have shown that prostate carcinoma-associated epigenetic biomarkers including GSTP1, RASSF1﻿, RARb and APC are detectable in our cultures to confirm that these primary PDCOs indeed originated from tumor cells." (PMID 34581895, 2021). "Disulfiram’s anticancer activity is mediated by its ability to suppress DNMT1 and through the reactivation of epigenetically silenced genes such as APC and RARB in prostate cancer cell lines (Section 1)." (PMID 33312959, 2020). "Taken together, RARβ and RARγ seem to play an antioncogenic role in prostate cancer through an inhibitory effect on AR signaling by competitive binding to AR-binding sites." (PMID 31212954, 2019). "RARB and SCGB3A1 proved to be independent variables that indicated a relative risk of there being prostate cancer of 1.14 (95 % CI 0.99–1.31, P = 0.058) and 1.10 (95 % CI 1.01–1.21, P = 0.028), respectively." (PMID 27576364, 2016). "We did perform a liver biopsy in a patient with prostate cancer receiving treatment, but unfortunately we were unable to assess the RARβ status." (PMID 22134508, 2012). "Many studies have suggested a role for RARβ in modulating the growth and survival of prostate cancer cells." (PMID 15266311, 2004). "In the retinoic acid receptor family, the overexpression of RARβ has been found to reduce the proliferation of prostate cancer cells, and RARγ may inhibit the development of prostate cancer by competitively binding AR binding sites." (PMID 39771106, 2024). "In addition, the RARβ promoter methylation status was higher in prostate cancer compared with nonmalignant tissues, suggesting reduced expression of RARβ in prostate cancer." (PMID 31212954, 2019).